TNF (tumor necrosis factor)
Diseases named in the same sentence as TNF in open-access papers (continued):
Sharing a sentence is not in itself a finding about the gene and the disease.
sarcopenia (continued). "The circulating factors in sarcopenia group were significantly lower: ALT, AST, ALB, γ-GT, CREA, UA, GLU, TG, LDL, GDF15, TNF-α and IL6." (PMID 40969368, 2025). "Studies have shown that several cytokines (TNF-α, CRP, and IL-6) play an important role in the pathogenesis of sarcopenia." (PMID 38397848, 2024). "In fact, elevated circulating levels of typical inflammaging mediators, such as Interleukin 6 (IL6), Tumor necrosis factor α (TNFα) and C-reactive protein (CRP), have been found in patients with sarcopenia." (PMID 38808117, 2024). "The highlighted sarcopenia biomarkers in this study included the low expression of IGF-I and TNF-α, high serum MSTN, and low serum vitamin D levels; however, the current literature is limited, and further research is required." (PMID 39769198, 2024). "The proinflammatory factors TNF-α, IL-6, and MCP1 are reported to be involved in the inflammatory responses leading to the development of sarcopenia." (PMID 38873561, 2024). "Elevated levels of IL-6, IL-1β, TNF-α, and CRP have been identified as potential contributors to the unfavorable outcomes of sarcopenia in PD-1 inhibitor treatment." (PMID 39101140, 2024). "As a result, proinflammatory cytokines such interleukin-6 and tumor necrosis factor alpha is upregulated, underscoring the critical function of ATGL in reducing age-related inflammation in sarcopenia." (PMID 39186818, 2024). "This study focused on randomized controlled trials (RCTs) that examined the effects of RT on interleukin-6 (IL-6), tumor necrosis factor-α (TNF-α), C-reactive protein (CRP), and interleukin-10 (IL-10) about sarcopenia." (PMID 38863698, 2024). "The highlighted sarcopenia biomarkers included the low expression of insulin-like growth factor (IGF-I) and tumor necrosis factor-α (TNF-α), along with high serum myostatin and low serum vitamin D levels." (PMID 39769198, 2024). "Inflammatory markers, such as tumor necrosis factor (TNF) and interleukin-6 (IL-6), as well as testosterone and growth hormones, have been identified for sarcopenia diagnosis." (PMID 38337720, 2024). "More specifically, among individuals with IBD, there is an upregulation TNF-α, IL-6, and interferon (IFN)γ, which all contribute to a higher overall systemic inflammatory burden and can lead to the development of sarcopenia." (PMID 38911683, 2024). "Mitochondrial and nuclear damage, decreased muscle‐specific PGC‐1α, apoptosis pathway, MAFbx and MuRF‐1‐mediated ubiquitination, and TNF‐α and INF‐γ‐induced inflammation all involve the mechanism of the development of sarcopenia." (PMID 38602220, 2024). "Both serum and local TNF-α were inversely correlated with GMI and relative muscle strength in our study, suggesting a role of TNF-α in the pathogenesis of sarcopenia." (PMID 36823174, 2023). "Some studies have indicated higher levels of pro-inflammatory cytokines, such as tumor necrosis factor (TNF)-α and interleukin (IL)-6, in individuals with sarcopenia." (PMID 38032288, 2023). "Em relação aos marcadores humorais e inflamatórios, não houve diferença significativa nas médias para os níveis séricos de PCR-as, IL-6, TNF-α, IGF-1 ou testosterona total entre os grupos com e sem sarcopenia ( Tabela 2 )." (PMID 37556651, 2023). "Pro-inflammatory cytokines, such as interleukin-6 (IL-6) and tumor necrosis factor-α (TNF-α), contribute to the process of protein homeostasis dysregulation and, consequently, to sarcopenia." (PMID 37173873, 2023). "Clinical studies have found increased levels of interleukin (IL)-6, IL-10, hypersensitive C-reactive protein (CRP), and tumor necrosis factor (TNF)-α in patients with coexisting COPD and sarcopenia." (PMID 37614743, 2023). "Patients with risk of sarcopenia were significantly younger and shorter than patients without risk of sarcopenia (Group A vs. Group B, age: 13.9 ± 2.8 years vs. 16.4 ± 1.9 years, p < 0.05; height Z score: 0.7 ± 1.1 vs. 0.4 ± 1.0, p < 0.05, respectively) at the initiation of anti-TNF therapy." (PMID 36477672, 2023).
sarcopenia (continued). "Moreover, we did not observe any association between IL-6 and TNF-α and presence of sarcopenia neither before (OR 0.90; 95% CI 0.25, 3.13, OR 1.60; 95% CI 0.73, 3.48) nor after controlling for potential confounders (OR 0.68; 95% CI 0.17, 2.77, OR 2.39; 95% CI 0.87, 6.55)." (PMID 35361818, 2022). "IL-6, TNF-α, and CRP levels have been reported to be significantly upregulated in patients with sarcopenia." (PMID 35162870, 2022). "Two inflammatory cytokines, including TNF-α and IL-4, were selected by PLS-DA to construct a model, which had an overall AUROC of 0.896 (95%CI 0.816–0.954) for sarcopenia." (PMID 36160136, 2022). "High levels of circulating pro-inflammatory cytokines (CRP, IL-6, TNF-α, etc.)have been found to correlate with low lower handgrip, decreased appendicular muscle mass and reduced knee-extension strength, indicating that these cytokines could be potential biomarkers of sarcopenia." (PMID 36499366, 2022). "Previous studies on markers of sarcopenia have mostly focused on serum creatinine and cystatin C, but also on related inflammatory mediators such as C-reactive protein (CRP), tumor necrosis factor-alpha (TNF-α), and interleukins (IL)." (PMID 36046129, 2022). "In the Copenhagen sarcopenia study, elderly women also had significantly higher levels of CRP, TNF-α, and IL-6, compared with middle-aged women and significantly higher levels of CRP, TNF-α, IL-1β, and IL-4 compared with young girls." (PMID 36291982, 2022). "Clinical studies reported aerobic exercise in people with sarcopenia increases IGF-1 and decrease muscle RING-finger protein-1 (MuRF-1), myostatin, and TNF-α." (PMID 35250869, 2022). "Another highlight in the present study was that in the sarcopenia group, both TSF and R-Leg-M predicted significant variations in CRP levels, while MAMA explained significant variations in TNF-α levels." (PMID 36291982, 2022). "However, the mechanism of TNF-α in the pathogenesis of sarcopenia remains unclear." (PMID 36160136, 2022). "Further studies are required to determine the impact of anti-TNFα, anti-interleukin and anti-integrin agents and other drugs used in the treatment of IBD, on sarcopenia in terms of muscle quantity, quality and performance." (PMID 33671473, 2021). "Neutrophil/lymphocyte ratio (NLR), tumor necrosis factor alpha (TNF-α), interleukin 6 (IL-6), C-reactive protein (CRP) are the markers most frequently associated with sarcopenic status and they could be considered as risk factors for the development of sarcopenia itself." (PMID 34944975, 2021). "Accumulating evidence demonstrated that the serum levels of tumor necrosis factor (TNF)-α, interleukin (IL)-6, and C-reactive protein (CRP) are elevated in sarcopenia, typically up to 2–4-fold higher than those in young controls." (PMID 32498474, 2020). "Sarcopenia is related to elevation in levels of inflammation markers, such as CRP, IL-621, and tumor necrosis factor (TNF)-α36." (PMID 30065297, 2018). "Taken together, it is possible that NOX generated H2O2 acts as a second messenger for Mstn induced TNF-α and downstream regulation of the UPS in aging skeletal muscle sarcopenia." (PMID 24093947, 2013). "Inflammatory cytokines such as interleukin (IL)-6 and tumor necrosis factor alpha (TNF-α) contribute, together with a reduced concentration of growth factors, to the development of sarcopenia." (PMID 20626909, 2010). "Using the OsteoSarcopenia cohort, we performed a proteomic analysis of human plasma‐derived EVs to examine the relationships between sarcopenia biomarkers (myostatin, adiponectin, P3NP, CRP and TNF‐α) and sarcopenia‐related factors (muscle mass, muscle function and muscle performance)." (PMID 40162588, 2025). "The levels of inflammatory markers such as TNF-α, high-sensitivity C-reactive protein (hs-CRP), and interleukin (IL)-6 are above average in patients with lower muscle strength, suggesting that sarcopenia might have a relationship with MAFLD." (PMID 40429815, 2025).
sarcopenia (continued). "Elevated levels of TNF‐α are characteristic of community‐dwelling older adults with frailty and sarcopenia, independent of age." (PMID 39764565, 2025). "TNF-α is positively correlated with sarcopenia regardless of age and the level of development of the country." (PMID 40507924, 2025). "Moreover, inflammatory cytokines such as TNF-α and IL-6, which are elevated in both T2DM and sarcopenia, have been shown to suppress mitochondrial function by inhibiting PGC-1α and inducing mitochondrial damage." (PMID 40869253, 2025). "For the models of E-DII and inflammatory mediators, AUC measurements for E-DII + cfDNA (AUC = 0.805) were considered a good discrimination, and the evaluation was as acceptable for cytokines IL-1β, IL-6, TNFα and CRP (0.7 < AUC < 0.8) i.e., it enabled sarcopenia diagnosis." (PMID 41345186, 2025). "The use of more sensitive inflammatory markers, such as IL-6 and TNF-α, may improve the characterization of systemic inflammation in low pSMI individuals and clarify the limited discriminatory capacity of hs-CRP in sarcopenia." (PMID 40909453, 2025). "The reductions in TNF‐α observed in both the CT and PRO+CT groups are particularly noteworthy, given the central role of this pro‐inflammatory cytokine in the development of sarcopenia and age‐related functional decline." (PMID 40994451, 2025). "After 6 months treatment with TNF inhibitors, our analysis revealed a significant increase in total lean mass, LMI, and lean mass on the arms, trunk, and gynoid area, as well as a reduction in the percentage of patients with sarcopenia." (PMID 40806763, 2025). "Furthermore, the combined therapy group presented the lowest TNF level and activated AMPK, which were possibly related to the pathogenesis of sarcopenia." (PMID 39859165, 2025). "Upon differentiation, C2C12 myotubes were treated with or without the TNF‐α, which is commonly used as an in vitro model for studying sarcopenia." (PMID 39076122, 2024). "Considering another component of sarcopenia in patients with PDAC, it has been proven that increased TNF-α and IL-1 concentrations lead to excessive transcription of leptin mRNA, resulting in higher serum leptin concentrations in patients with PDAC and decreased appetite." (PMID 39458563, 2024). "Sarcopenia affects the immune response, leading to the development of chronic low-grade inflammation (LGI), which results in the constant release of pro-inflammatory cytokines, among which tumor necrosis factor (TNF) stands out." (PMID 38656072, 2024). "Our study does not support this claim like two negative clinical trials using TNF‐α blocking drugs for the prevention of cancer‐related sarcopenia." (PMID 38481033, 2024). "Suggested potential sarcopenia biomarkers are myostatin (MSTN), insulin-like growth factor 1 (IGF-I), C-terminal agrin fragment (CAF), interleukin-6 (IL-6), tumor necrosis factor alpha (TNF-α), and vitamin D." (PMID 39769198, 2024). "The association of IL-10 to TNF-α ratio (aOR 0.98, 95% CI 0.97–0.99) and IL-10 (aOR 2.22, 95% CI 0.05–0.98) with MCR were independent of sarcopenia and BF%." (PMID 37371414, 2023). "The area under curve of the ROC analysis to discriminate participants with and those without sarcopenia was 0.65 (95% CI, 0.54-0.75) for TNF-α, 0.74 (95% CI, 0.65-0.84) for IL-1β, 0.80 (95% CI, 0.71-0.88) for IL-6 and 0.55 (95% CI, 0.44-0.66) for IL-15." (PMID 38032288, 2023). "Only low IL-10 and IL-10 to TNF-α ratio were significantly associated with MCR, independent of sarcopenia and body fat percentage." (PMID 37371414, 2023). "In our study, we noted lower values of inflammatory markers (CRP, CRP/albumin ratio, TNFα, IL-6, IL-1β, cfDNA) in the no-sarcopenia group, as opposed to the sarcopenia group." (PMID 37465171, 2023).
sarcopenia (continued). "In the current study, we identified that aged mice with sarcopenia presented a chronic low-grade inflammation with a high level of serum TNF-α and local TNF-α overexpression in GM, accompanied by evidence of GSDME-mediated pyroptosis and activation of apoptotic caspase-8/-3 in skeletal muscle cells." (PMID 36823174, 2023). "A growing body of evidence indicates that sarcopenia may impact metabolic abnormalities involving detrimental myokines and hormonal substances, such as Vitamin D, Irisin, IL-6, RANKL, and TNF-α." (PMID 37999432, 2023). "Furthermore, elevated concentrations of TNF-α, IL-6 and CRP are frequently identified in sarcopenia patients These cytokines probably trigger the activation of the ubiquitin-protease system and develop sarcopenia." (PMID 37932727, 2023). "Chronic inflammation also affects sarcopenia, as pro-inflammatory cytokines such as interleukin-6 (IL-6), TNF-α, and C-reactive protein (CRP) increase adiposity and impair the protein synthesis pathway in skeletal muscles, which promotes the pathogenesis of sarcopenia." (PMID 36474318, 2023). "Of note, elderly ED patients with sarcopenia did not exhibit higher concentrations of IL-6 and TNF-α, which indicated that possible sarcopenia did not correlate with systemic inflammation." (PMID 36714126, 2022). "In this cross-sectional study, we aim to compare inflammatory factors levels, including IL6, CRP, and TNFα, between sarcopenia and non-sarcopenia in Iranian adults." (PMID 35361818, 2022). "Interestingly, inflammation and mDAMPs synergistically contribute to sarcopenia; for example, mDAMPs can activate the Toll-like receptor (TLR) pathway and trigger NF-κB signaling, thus increasing the expression of IL-6 and TNF-α." (PMID 35954203, 2022). "Comparisons of living habits, disease status, biochemical indexes, and levels of interleukin (IL)-4, IL-6, IL-8, IL-10, and tumor necrosis factor (TNF)-α in sarcopenia and non-sarcopenia participants were made in this study." (PMID 36160136, 2022). "Our study found that the tumor necrosis factor α level in patients with sarcopenia was higher than that of patients without sarcopenia, which concludes that inflammatory factor network disorder is associated with sarcopenia." (PMID 36160136, 2022). "Lastly, MAMA was an independent predictor of TNF-α, explaining 9% of the variances perceived among those without sarcopenia (R2 = 0.09; p < 0.05)." (PMID 36291982, 2022). "The serum levels of resistin and TNF-α were significantly higher in patients with sarcopenia than in patients without sarcopenia." (PMID 35903456, 2022). "Therefore, we next analyzed the relationship between resistin and TNF-α expression in patients with COPD and the predictive value of the resistin level for sarcopenia." (PMID 35903456, 2022). "Surprisingly, older adults with possible sarcopenia did not concurrently exhibit a higher level of IL-6 and TNF-α than non-sarcopenia subjects in our study." (PMID 36714126, 2022). "Biologic therapy, including anti-TNF alpha agents and newer anti-interleukin, anti-integrin, and JAK inhibitors agents used for treatment of IBD, might reduce sarcopenia, blocking the catabolic effects on skeletal muscle tissue." (PMID 34326845, 2021). "Systemic levels of cytokines such as Tumor Necrosis Factor-α (TNF-α) and other hepatokines such as Fibroblast growth factor 21 (FGF21) may modulate sarcopenia and muscle function respectively as well." (PMID 34040583, 2021). "We have explored a large set of biomarkers in patients with a recent hip fracture with and without sarcopenia and shown that only TNF‐α and CAT levels were different between groups." (PMID 31912666, 2020). "Infliximab, a TNF-α antibody, increased both muscle volume and strength in CD patients, and moreover, colectomy increased SMI and serum albumin with a decrease in the prevalence of sarcopenia in UC patients." (PMID 32784808, 2020).
sarcopenia (continued). "The induction of immortalized skeletal muscle cell lines to imitate pathophysiology of sarcopenia by using several substances including oxidative stress (H2O2), sphingophospholipid (ceramide or palmitate), inflammatory cytokines (TNF-α) as well as dexamethasone are discussed in the present review." (PMID 32498474, 2020). "The TNFα concentration was significantly higher in males with than without sarcopenia (3.06 ± 1.95 pg/mL vs. 6.07 ± 3.27 pg/mL, p < 0.01)." (PMID 31581569, 2019). "Transplanting bone marrow cells from wild‐type mice into TNF‐α‐null recipients also increased sarcopenia, although transplantation did not restore the age‐related change in muscle fiber phenotype." (PMID 30256507, 2018). "Elevation of inflammatory proteins, such as interleukin (IL)-6 and tumor necrosis factor alpha (TNF-α), may lead to various physical changes, including a decrease in muscle mass and adipose tissue in patients with sarcopenia." (PMID 28359307, 2017). "This is in line with the suggested negative effect of TNF-α on muscle regeneration in Duchenne muscular dystrophy or in sarcopenia." (PMID 25630602, 2015). "Third, specific pro-inflammatory cytokines such as IL-6, TNF-α, and IL-1β–known to play direct roles in the pathogenesis of sarcopenia—were not available in the NHANES dataset and, thus could not be analyzed." (PMID 40708651, 2025). "The dependent variable (sarcopenia) was a binary classification (0= absent, 1= present), and continuous independent variables included levels of four inflammatory cytokines: IL-2, IL-6, IL-8, and TNF-α." (PMID 40265008, 2025). "In this context, recent investigations have confirmed the high levels of certain proinflammatory markers and cytokines (i.e., tumor necrosis factor alpha (TNF-α), interleukin-6 (IL-6), etc.)in people with sarcopenia, suggesting that VAT mass may act directly or indirectly in SO physiopathology." (PMID 38892578, 2024). "Additionally, sarcopenia and MDD show a direct relationship to a large extent due to the immunoinflammatory alterations they share, such as elevated levels of IL-6, CRP and TNF-α, responsible for the induction of numerous systemic changes observed in patients with sarcopenia and MDD." (PMID 39681901, 2024). "High levels of pro-inflammatory factors interleukin-6 (IL-6), tumor necrosis factor-α (TNF-α), and C-reactive protein (CRP) may induce sarcopenia by affecting protein balance synthesis, and dysregulation of the inflammation may also be involved in the pathophysiological mechanisms of MCI." (PMID 38148730, 2023). "In our study, sarcopenia was independent of age, disease severity accessed by wPCDAI, and location of disease but as previously noted was more frequently seen in patients with the perianal disease, and those patients in higher extent required anti-TNF therapy." (PMID 37686870, 2023). "Moreover, both sarcopenia and NAFLD are characterized by a chronic inflammatory state shaped by the over secretion of pro-inflammatory cytokines, such as tumour necrosis factor alpha (TNFα) and interleukin 1 (IL1)." (PMID 35052859, 2022). "Therefore, our study included ND-CKD patients alone and evaluated sarcopenia as a hard outcome; sarcopenia components including muscle mass index, strength, and physical performance; and inflammatory indicators including hs-CRP, TNF-α, and interleukin-6." (PMID 36566275, 2022). "TNF may well be found in sarcopenia and MetS, but is not as pronounced as found in the current study." (PMID 35100595, 2022). "Furthermore, we did not observe any remarkable association between inflammatory biomarkers including IL-6 (OR 1.15; 95% CI 0.31–4.28), TNF-α (OR 0.68; 95% CI 0.17–2.77), and hs-CRP (OR 2.39; 95% CI 0.87–6.55) and the presence of sarcopenia even after controlling for plausible confounders." (PMID 35361818, 2022).